FGF2 (fibroblast growth factor 2)
Diseases named in the same sentence as FGF2 in open-access papers (continued):
Sharing a sentence is not in itself a finding about the gene and the disease.
cancer (continued). "The stimulatory effect of FGF2 released from cancer cells was higher in macrovascular endothelial cells than in microvascular cells." (PMID 34830951, 2021). "Further studies were performed to examine a cancer-free cohort of subjects for serum FGF2 and activity on colony formation." (PMID 34685650, 2021). "In future work, it will be interesting to address the role of FGF2 rs1960669 in mCRC cancer survival and prognosis." (PMID 33573134, 2021). "For example, overexpression of FGF2 and FGF1 are linked with both in vivo and in vitro resistance to cancer drugs such as doxorubicin, 5-fluorouracil and paclitaxel." (PMID 34830836, 2021). "SETD2 knockdown would lead to the abundance of the IIIb relative to the IIIc transcripts in NCI H522 and NCI H1299 cells and then attenuate cancer cells migration, invasiveness, and proliferation in the presence of FGF-2." (PMID 34715919, 2021). "It has been found that the concentration of FGF-2 is increased in the urine of patients with various cancers." (PMID 34095461, 2021). "Fgf-2 and its receptor Fgfr1 play a crucial role in both stromal and cancer cells in enhancing cancer cell survival." (PMID 34722255, 2021). "FGF1 and FGF2 can be overexpressed by cancer cells and have been correlated with advanced tumour stage." (PMID 33918004, 2021). "FGF2 is considered a critical mediator of EMT in numerous cancers, such as bladder cancers, breast cancer, and HCC." (PMID 33802841, 2021). "VEGFA and FGF2 are both targets of miR-503 in cancer; therefore, miR-503 plays an anti-angiogenic role in tumorigenesis." (PMID 34095461, 2021). "We developed conjugates based on fibroblast growth factor(FGF2) with improved biophysical and biological properties for theefficient killing of cancer cells overproducing fibroblast growthfactor receptor 1 (FGFR1)." (PMID 34542998, 2021). "For cancer cells, intracellular delivery of FGF-2 via ABN uptake produced cytotoxic effects that correlated with significantly higher levels of activated nuclear ERK1/2." (PMID 32230722, 2020). "FGF2 is necessary to maintain self-renewal in adult and embryonic stem cells, including cancer stem cells (cancer stem cells)." (PMID 32963755, 2020). "A report showed KDM2B’s expression in primary MEFs and cancer cells is induced by FGF-2 via CREB phosphorylation and activation, downstream of DYRK1A kinase." (PMID 31317506, 2020). "FGF2 is only sporadically reported as increased in human cancers, but radiotherapy has been shown to increase expression of FGF2 in human rectal and cervical cancers." (PMID 32792542, 2020). "Our results provide new insight into the molecular function and mechanism of API5 and nuclear FGF2 as novel components of the mRNA export machineries and suggest a new therapeutic opportunity for the regulation of oncogenic gene expression in cancers." (PMID 32383752, 2020). "It is likely that initially, FGF2 is expressed as a paracrine factor by stromal cells, and during cancer progression or following therapy, there is a switch to an autocrine expression." (PMID 33425737, 2020). "Our novel intracellular delivery method of FGF-2 via nanoparticles resulted in increased cancer cell death via increased nuclear ERK1/2 activation." (PMID 32230722, 2020). "The switch of the PROX1 expression level in different cancer stages was suggested to be negatively regulated by fibroblast growth factor 2 (FGF2)." (PMID 32370142, 2020). "API5 (APoptosis Inhibitor 5) and nuclear FGF2 (Fibroblast Growth Factor 2) are upregulated in various human cancers and are correlated with poor prognosis." (PMID 32383752, 2020). "Oncostatin M (OSM) is a member of IL-6 family cytokines with diverse activities, and it can stimulate angiogenesis by enhancing FGF-2 expression and can in vitro induce mesenchymal- and cancer stem cell-like phenotypes in cancer cells." (PMID 32422991, 2020). "The studies have shown that FGF2 is frequently dysregulated in cancer, especially in advanced stages of disease." (PMID 33381388, 2020).
cancer (continued). "FGF2, which was highly expressed in both cancer 4 cells and CSCs, interacted with the receptor FGFR1 in osteoclasts." (PMID 33162821, 2020). "To further assess Fgf2 expression in cancers, we analysed the relationship of Fgf2 expression to immune subpopulation markers in human CRC using GSEA analysis." (PMID 32792542, 2020). "FLT1 can combine with VEGFR-A, VEGFR-B, and FGF-2, promoting proliferation of endothelial cells in the process of angiogenesis in various cancer 22-24." (PMID 32788880, 2020). "This study is the first to report on the intracellular delivery of FGF-2 by ABNs and its cytotoxic effects on a cancer cell line." (PMID 32230722, 2020). "As a member of the fibroblast growth factor (FGF) family, FGF2 is a key mitogen in tissue homeostasis and cancer." (PMID 32977766, 2020). "The same authors conducted a series of in vitro experiments on A549 cancer cells that further proved the implication of miR-135a in the regulation of different proangiogenic factors, with an emphasis on FGF2." (PMID 33121202, 2020). "FGF2 is frequently dysregulated in cancer, especially in advanced stages of hematological and solid tumors, working as a potent proangiogenic growth factor." (PMID 32695805, 2020). "The cancer prompting role of miRNA-203 is exerted through fibroblast growth factor 2 (FGF2), a direct target of miRNA-203." (PMID 31597272, 2019). "This scenario provides a rationale for the observed induction of cell death triggered by the combination of FGF2 and bortezomib in these murine cancer cells." (PMID 30422399, 2019). "Soluble factors, such as FGF2, secreted autonomously by cancer cells undergoing EMT, activate FGFR(IIIc) and ERK pathways to sustain high ZEB1/2 levels." (PMID 31682640, 2019). "Following that, abundant distribution of FGF2/4 in the cancer microenvironment further stimulates FGFR(IIIc) isoforms in cancer cells undergoing EMT and sustains EMT phenotypes even in the vascular and lymphatic systems." (PMID 31682640, 2019). "Despite the many different protumor roles attributed to FGF2 signaling, a set of articles unequivocally demonstrate that FGF2 can also induce cytostatic and cytotoxic responses in different cancer cells, both in vivo and in vitro." (PMID 30422399, 2019). "We show that FGF2 enhanced replication and proteotoxic stresses in a K‐Ras‐driven murine cancer cell model, and combinations of FGF2 and proteasome or DNA damage response‐checkpoint inhibitors triggered cell death." (PMID 30422399, 2019). "Ilkow CS and coll. demonstrated that FGF2 produced by CAFs enhanced OV replication in cancer cells and reduced the anti-viral proteins produced by cancer cells in culture." (PMID 31636245, 2019). "Our results implicate that FGF2 signaling overactivation can efficiently disrupt proteostasis, resulting in a vulnerability common to cancer cells with diverse origins and driver oncogenic lesions." (PMID 30422399, 2019). "Previous studies have shown that cancer-associated fibroblasts (CAF) secrete a variety of cytokines in and high levels of growth factors such as EGF, TGF-β, HGF, and FGF-2 into CAF-conditioned media." (PMID 31491033, 2019). "However, the results for A673, SK‐N‐MC, and TC‐32 cells, in which FGF2 or bortezomib alone had minor effects on long‐term cell viability but their association was highly toxic, highlight the therapeutic potential of this combination for inducing cancer cell death." (PMID 30422399, 2019). "On signaling level cancer associated fibroblasts (CAFs) in 3D co-cultures have also been linked to CRC cell migration and invasion, partly dependent on FGF-2 and FGFR signaling." (PMID 31068603, 2019). "Previous studies have shown that estrogens acting either through ER or GPER up-regulate FGF2 expression and secretion in both normal and cancer cells." (PMID 30866584, 2019).
cancer (continued). "Doxorubicin (Dox)-induced cardiotoxicity, a limiting factor in the use of Dox to treat cancer, can be mitigated by the mitogenic factor FGF2 in vitro, via a heme oxygenase 1 (HO-1)-dependent pathway." (PMID 30159756, 2018). "Transforming growth factor-β (TGF-β), platelet-derived growth factor (PDGF), tumor necrosis factor (TNF), stromal cell-derived factor 1 (SDF1) and fibroblast growth factor 2 (FGF2) are key mediators of fibroblast activation in cancer development." (PMID 30477536, 2018). "We decided to develop FGF2 dual warhead conjugate as potential therapeutic agent for treatment of drug-resistant cancers overproducing FGFRs." (PMID 30029518, 2018). "To improve the FGF2-based conjugate and overcome potential heterogeneity and resistance of cancer cells to a single-drug treatment, we decided to design FGF2 dual warhead conjugate with two mechanistically different cytotoxic agents: MMAE and α-amanitin." (PMID 30029518, 2018). "Genes regulated by TH-binding to integrin αvβ3 include fibroblast growth factor 2 (FGF2), matrix metalloproteinase 2 (MMP2), HIF1A, and cyclooxygenase 2 (COX2), which have been associated with cancer development and angiogenesis." (PMID 30360449, 2018). "Cancer is a systemic disease, and studies showed that paracrine factors such as hepatocyte growth factor, Wnts, basic fibroblast growth factor (or FGF2), and some cytokines from the microenvironment contribute to PCa initiation, progression, and metastasis." (PMID 29911070, 2018). "Here, we expand the idea of FGF-based targeted anti-cancer cytotoxic drugs by combining FGF2 with two cytotoxic compounds displaying independent modes of action." (PMID 30029518, 2018). "Dasatinib reduced SRC phosphorylation in cancer cells and or Erdafitinib inhibited FGF-2 production in fibroblasts." (PMID 30065926, 2018). "The FGF2 gene presents a 3’ UTR shortening event that has been reported previously in several cancer cell lines." (PMID 30005633, 2018). "A concern with using FGF2 as a cardioprotective strategy against Dox is the possibility of undesirable effects on cancer cell proliferation and survival." (PMID 30159756, 2018). "Taken together, these results suggest that API5 confers CSC-like property in cancer cells through the FGF2-NANOG molecular axis." (PMID 28092370, 2017). "Further analyses of 407 carcinomas in the TCGA data set revealed that tumors expressing high levels of FGF-2 tend to also express high levels of Akt3." (PMID 28515962, 2017). "This review focuses on the prognostic significance of FGF2 in cancer with emphasis on therapeutic intervention strategies for solid and hematological malignancies." (PMID 27007053, 2016). "FGF2 expression in sera quantified by ELISA was strongly increased in cancer patients compared to healthy donors." (PMID 27007053, 2016). "Identifying patients with advanced, relapsed or refractory cancers that would benefit from FGF2/FGFR signaling inhibition will allow for better treatment options of those patients in the era of personalized medicine." (PMID 27007053, 2016). "FGF2 expression in cancer surgical sections has been evaluated using immunohistochemical, Western blot, and qRT-PCR techniques." (PMID 27007053, 2016). "In vitro experimental settings have indicated that extracellular FGF2 affects proliferation, drug sensitivity, and apoptosis of cancer cells." (PMID 27007053, 2016). "Cancer cells treated with IMB-R1 displayed impaired FGF2 signaling, were unable to grow and instead underwent apoptosis." (PMID 26201468, 2015). "FGF-2, besides being expressed in cancer and precancer, was also found in 26.92% cases of healthy controls in the present study." (PMID 26465941, 2015). "In conclusion, we show that fibroblasts induce cell-contact-dependent CRC cell migration and invasion under 2D and 3D conditions in vitro through surface associated FGF-2, FGFR-mediated activation of the SRC in cancer cells and αvβ5-mediated adhesion." (PMID 25973543, 2015).
cancer (continued). "mRNA level of FGF-2 was also much higher in fibroblasts compared to cancer cells, however FGF-2 protein levels were identical in culture supernatants of fibroblasts, cancer cells and co-cultures." (PMID 25973543, 2015). "FGF-2 is involved in the invasion of cancer cells and the proliferation of fibroblasts around cancer cells in an autocrine or paracrine fashion." (PMID 26465941, 2015). "Presented results demonstrate that fibroblasts promote CRC cell migration and invasion through direct cell-cell contact involving fibroblast cell surface associated FGF-2 and FGF receptors (FGFR) - integrin αvβ5-SRC dependent signaling in cancer cells." (PMID 25973543, 2015). "FGF2 signaling drives a wide range of oncogenic events such as proliferation, migration and survival in multiple cancer cell types." (PMID 26056081, 2015). "Next we looked for an intracellular signaling pathway mediating FGF-2/FGFR-induced cancer cell elongation, migration and invasion." (PMID 25973543, 2015). "Next we interrogated these physiomimetic cultures for localisation of FGFR1 and FGF2 in specific cellular compartments (within both cancer and stromal cells), upon PD173074 treatment." (PMID 24503018, 2014). "The increase in ECM synthesis by PSCs upon exposure to cancer cells is thought to be mediated by transforming growth factor beta 1 (TGFβ 1) and fibroblast growth factor 2 (FGF2)." (PMID 24592240, 2014). "In contrast to the cytoplasmic expression of FGF2 in cancer cells, many (∼35%) myo-fibroblasts (activated PSCs) expressed nuclear FGF2, as evident from co-localisation analysis." (PMID 24503018, 2014). "At a molecular level, FGF2 binds to multiple membrane bound receptors in human cancers, including SDC1, and this receptor binding can trigger multiple signaling pathways, including those involved in cell proliferation and survival." (PMID 23988031, 2013). "Several lines of evidence indicate that FGF2 plays an important role in the invasive properties of human cancer cells." (PMID 23554977, 2013). "FGF2 has been shown to activate the MAPK/ERK pathway in various cancer cells, and we show in OVCAR-4 and SKOV-3 cells that ZEB1 expression is MAPK/ERK-dependent." (PMID 23554977, 2013). "These FGF2’s effects point to unsuspected vulnerabilities in cell cycle homeostasis of Ras-dependent malignancies, which are quite common among human cancers." (PMID 23991123, 2013). "KEGG pathway analysis revealed that the common genes expressed in FGF2 and IL-11 are enriched for cell adhesion, tight junction, insulin signaling and cancer pathways." (PMID 24194720, 2013). "We here address the potential role of FGF2 in DNA repair in the A431 carcinoma cells (MP cells) and in a small sub-population which expresses characteristics of cancer stem cells (SP cells)." (PMID 22732006, 2012). "KEGG enrichment analysis showed that VEGFA and OPN participate in the ‘focal adhesion’ pathway (adjP=0.0002) and VEGFA along with FGF2, both participate in ‘pathways in cancer’ (adjP=0.0003)." (PMID 22895562, 2012). "We detected a considerable inter-individual heterogeneity of paracrine interactions but identified FGF2, HB-EGF, heparanase-1 and SDF1 as factors that were consistently responsible for the activity of carcinoma-associated fibroblasts." (PMID 23056402, 2012). "We found that SP cells were characterized by specific FGF2 expression and activities, which differ from the main population of carcinoma cells." (PMID 22732006, 2012). "In agreement with our previous work on immortalized mammary fibroblasts, FGF-2 was identified as important paracrine growth promoting factor in CAF from all but three carcinomas." (PMID 23056402, 2012). "In the present study, we characterized DNA repair and FGF2 expression in SP cells isolated from A431 cells and compared them to the main population of carcinoma cells (MP cells)." (PMID 22732006, 2012).
cancer (continued). "We postulate that carcinoma stem cells would be intrinsically primed to rapidly repair DNA damage by a high constitutive level of nuclear FGF2." (PMID 22732006, 2012). "This further supports the notion that FGF-2 can effectively promote the survival of cancer cells exposed to cytotoxic drugs." (PMID 21625473, 2011). "FGF-2 has been identified as an adverse prognostic factor for many cancer patients and Seckl and Pardo have demonstrated its relevance for drug resistance." (PMID 21625473, 2011). "LMM FGF-2 is a well-established autocrine/paracrine regulator of normal fibroblast proliferation and invasiveness and tumorigenic potential of carcinoma cells." (PMID 19544431, 2009). "FGF2 critically modulates mesenchymal-to-epithelial transition, which is now widely accepted to contribute to carcinoma invasiveness." (PMID 18211683, 2008). "Extending upon these studies, we performed immunohistochemical staining of high-grade dysplastic lesions (HSIL/CIN3) or carcinomas of the human cervix, revealing prominent expression of FGF-2 in stromal cells (and unpublished data)." (PMID 18232728, 2008). "There is thus substantial evidence to indicate that IGFs and FGF-2 are critical survival factors for cancer cells, and that metastases development is indeed dependent on such survival signals." (PMID 12838321, 2003). "Next, we grouped them into cytokines associated with pre-cancer or the initiation stage of HCC (IL-6, TGF-β, MCP-1, FGF2, IL-2, IL-8, IL-12p40, IL-12p70, IL-18, IP-10, TNF-α, and IFN-γ), the early stage of HCC (OPN, GDF-15, RANTES, and VEGFA), and the advanced stage of HCC (IL-10, and MIP-3)." (PMID 41219858, 2025). "Interestingly, six genes among these (ABCB1, FGF2, CXCR4, IL6, PSMB9, and CLU), as well as UGCG, are known to be highly associated with cancer resistance to platinum-based chemotherapy." (PMID 40507922, 2025). "FGF2 produced by CAFs promotes cancer cell growth and migration through interaction with FGFR1." (PMID 40136652, 2025). "For instance, interleukin (IL) 6 (IL-6), transforming growth factor beta (TGF-β), fibroblast growth factor 2 (FGF2), monocyte chemoattractant protein 1 (MCP-1), and vascular endothelial growth factor A (VEGFA) have been linked to the pre-cancer or initiation (formation) of HCC." (PMID 41219858, 2025). "However, in several types of cancer, FGF2 expression was elevated (i.e., colorectal cancer, gastric cancer, ovarian cancer, and pancreatic cancer)." (PMID 39766329, 2024). "Additionally, it diminishes the expression of the VEGF and fibroblast growth factor 2 (FGF2) proteins, restraining the tubular formation of endothelial cells within cancer cells, consequently exerting a suppressive effect on angiogenesis." (PMID 38475570, 2024). "This is the case for example of FGF2, a ligand known to promote cancer cell stemness." (PMID 39349458, 2024). "Similar to other gene-silencing agents, targets of ribozyme for anti-cancer therapy are genes that are cancer-inducing, such as mutant K-ras and fibroblast growth factor-2 (FGF-2), or important for cancer survival, such as γ-Glutamylcysteine synthetase (γ-GCS) and multiple drug resistance 1 (MDR-1)." (PMID 39407665, 2024). "Therefore, more studies are required, encompassing different cancer types and with longer study times, to better clarify the dosimetric aspects of radiolabeled FGF-2." (PMID 38672507, 2024). "Cancer-associated fibroblasts (CAFs) are the most abundant stromal cells within the TME, typically activated from resident fibroblasts in response to stimuli such as TGF-β, platelet-derived growth factor (PDGF), and fibroblast growth factor-2 (FGF-2)." (PMID 39770505, 2024). "The epithelial cell usually expresses the FGFR-3b isoforms, but during the EMT process, TGF-β induced the isoform switching of fibroblast growth factor receptors (FGFR-3c), causing the cells to become sensitive to FGF-2, inducing EMT and promoting cancer progression." (PMID 38672507, 2024).